ENSG00000280371 ( gene)
Diseases named in the same sentence as ENSG00000280371 in open-access papers (continued):
Sharing a sentence is not in itself a finding about the gene and the disease.
prostate carcinoma (24 papers, 2007 to 2025). A carcinoma that arises from epithelial cells of the prostate gland. "NKX3-1 is a well known tumor suppression gene, whose decreased expression has been associated with prostate cancer." (PMID 32986714, 2020). "In addition, treatment of MM cells with GSK2606414 resulted in the upregulation of HERPUD1 gene expression, which is an ER stress responsive gene that was previously connected to reduced tumor-associated expression in prostate cancer cells." (PMID 33028016, 2020). "PMEPA1 is an androgen-responsive gene initially studied in the context of prostate cancer androgen-regulated gene networks." (PMID 40244296, 2025). "Cluster B included PTEN, a common mutation in mCRPC, and MSH6, a mismatch repair gene seen in 1% of prostate cancer cases." (PMID 38050021, 2023). "Zn finger protein ZNF185 is a LIM domain gene the expression of which is downregulated in several epithelial cancers including prostate cancer." (PMID 36551962, 2022). "Consistently, it has been revealed that SPOP serves as a tumor repressor gene in gastric, colorectal, and prostate cancers." (PMID 35461336, 2022). "RNF7, an apoptosis-sensitive gene, has been shown in several previous studies to play an important role in the development and progression of tumors such as prostate cancer and lung cancer." (PMID 33414811, 2020). "It encodes a mitochondrial enzyme that can protect cell from oxidative damage, and has been known as a tumor suppressor gene in human prostate cancer." (PMID 30367578, 2018). "Overexpression of GPX3 in prostate cancer cell lines seemed to restrain tumor growth and metastasis through downregulation of c-met, a receptor tyrosine tumor transforming gene involved in a variety of cellular processes." (PMID 25970749, 2015). "We have shown that OGR1 functions as a tumor metastasis suppressor gene when it is over-expressed in human prostate cancer cells in vivo." (PMID 19479052, 2009). "TMEFF2 codifies an androgen-regulated transmembrane protein, normally restricted to the brain and prostate tissues, initially described as a tumor suppressor gene for its inhibition of cell growth and hypermethylated status in several tumors, including prostate carcinomas." (PMID 25595908, 2015). "Consequently we propose that zinc is a tumor-suppressor agent; and Zip1, along with Zip2 and Zip3, is a tumor suppressor gene in prostate cancer." (PMID 17550612, 2007). "Therefore, we hypothesized that PLZF acts as the tumor-suppressor gene to improve the poor prognosis in prostate cancer patients." (PMID 32349303, 2020). "We determined whether FOXD1 is a hypoxia-related gene, and explored the roles of FOXD1 in prostate cancer cell growth and glycolysis." (PMID 41214670, 2025). "We also conclude that VPA has differential effects on the metastasis suppressor gene and invasion ability between non-metastatic and metastatic prostate cancer cells." (PMID 26692161, 2015). "Indeed, MT3 has been considered for a long time as a non metal-inducible gene in normal astrocytes and neurons cultures, but recently Wei and co-workers showed MT3 induction after zinc treatment in prostate cancer cells." (PMID 20885975, 2010).
glioma (22 papers, 2010 to 2024). A benign or malignant brain and spinal cord tumor that arises from glial cells (astrocytes, oligodendrocytes, ependymal cells). "miR-204 has been reported to act as a tumor suppressor gene in various malignancies, including glioma." (PMID 38680092, 2024). "In summary, LARP4B is a tumor-suppressor gene of glioma; the potential mechanisms involved, however, remain to be probed further." (PMID 36552760, 2022). "MiR-330-5p has been confirmed to be a tumor-suppressor gene in many cancers including papillary thyroid cancer, glioma, oesophageal adenocarcinoma and melanoma." (PMID 33176280, 2020). "ERCC1 is a DNA repair gene whose protein product plays an important role in nucleotide excision repair; both its protein and mRNA expression is reduced in colon cancer and glioma." (PMID 27410681, 2016). "In another study, sensitization of glioma cells to TMZ by JNK inhibitors was observed in MGMT expressing cells due to an impact of JNK on the basal expression of this DNA repair gene." (PMID 26418950, 2015). "Along with the role of Cx43 as a channel in glioma, studies show that Cx43 can act as a tumor suppressor gene, as well." (PMID 24904426, 2014). "The downregulation of miR-23a expression in glioma cell lines suggests that miR-23a may be a tumor suppressor gene of oral squamous cell carcinoma." (PMID 35342401, 2022). "Our previous study showed that miR-204-5p is a tumor suppressor gene in glioma." (PMID 32489472, 2020). "Meanwhile, the present study provides evidence that DACT2 as a tumor suppressor gene could inhibit growth and induce apoptosis of glioma cells by suppressing YAP through Wnt/β-catenin signaling pathway." (PMID 28796248, 2017). "However, in glioma and some other cancers, miR-146b-5p expression is downregulated and acts as an tumor suppressor gene." (PMID 27166258, 2016). "TRPM3 may play a vital role as a tumor suppressor gene in glioma." (PMID 38680092, 2024). "Collectively, although these investigations showed that NDRG1 might be suggested to have the potential of a tumor suppressor gene in glioma, several factors might lead to poor prognosis and reduced OS, such as tumor environment (e.g., hypoxia, stress condition) and genotoxic changes by chemotherapy." (PMID 35448004, 2022). "Therefore, miR-450a-5p may serve as a tumor suppressor gene in glioma." (PMID 32820249, 2020). "Since YAP is a well-known tumor-promoting gene in gliomas, we speculate that SU4312 may repress the proliferation, invasion and migration of gliomas by inhibiting the transcription and expression of YAP." (PMID 36013004, 2022).
lung carcinoma (22 papers, 2013 to 2026). "Multiple studies have indicated that GPRC5A serves as an important tumor suppressor gene in lung cancer." (PMID 38634049, 2024). "Silencing SLIT3 expression enhanced cell proliferation and migration, indicating potential characteristics of a tumor suppressor gene of SLIT3 in non–small-cell lung cancer (NSCLC)." (PMID 39479352, 2024). "In view of our data indicating that Uc.339 behaves as a "growth metastasis promoting gene" in lung cancer, we next tried to determine the possible mechanism of this phenotype." (PMID 35399708, 2022). "Cell experiments confirmed the role of TRIM58 as a tumor suppressor gene in lung cancer and overexpression of TRIM58 inhibited the malignant phenotype of tumors." (PMID 34434284, 2021). "Our analyses identified AP1S3 as a second clinically relevant AP-1 adaptor gene in lung cancer." (PMID 41438582, 2026). "Our correlation analysis revealed that the correlation between IL22RA1 with macrophage was significantly obvious suggesting that the IL22RA1 might be an immune-related gene in lung carcinoma." (PMID 34040139, 2021). "In summary, our study demonstrates that FTX may function as a tumour suppressor gene and regulate lung cancer development through acting as a sponge of miR‐200a‐3p to promote FOXA2 expression." (PMID 32176463, 2020). "However, a recent study unveiled KDM6A as an important tumor suppressor gene in lung cancer with evidence gained from human lung cancer specimens and transgenic NSCLC mouse models." (PMID 30002791, 2018). "These indicated that miR-21-5p and miR-196a-5p might serve as oncogene, and miR-218-5p might act as tumor suppressor gene in lung cancer." (PMID 27247934, 2016). "Because previous studies have shown that MR expression is down regulated in both colorectal and lung cancers, it has been suggested that MR may act as a tumor-suppressor gene." (PMID 23555666, 2013). "We demonstrated that PARK2 may be a bona fide tumor suppressor gene that may be responsible for the development of progression lung cancer with COPD, suggesting PARK2 as a potential target to reduce the risk of COPD and lung cancer." (PMID 27329585, 2016). "Therefore, it is suggested that it might act as a tumor suppressor gene for lung cancer." (PMID 36067196, 2022). "The classical tumor EMT inducer TGF-β further confirmed that TAp63α acts as a tumor suppressor gene in lung cancer development and the inhibition of TAp63α triggered the EMT process in lung cancer." (PMID 33748140, 2021). "Previous studies have indicated that CTNNBIP1 may be a tumor suppressor gene, but its anti-migration properties have not yet been reported for human lung cancers." (PMID 31766223, 2019).
ovarian carcinoma (21 papers, 2009 to 2024). A malignant neoplasm originating from the surface ovarian epithelium. "Furthermore, miR-1-3p could be a tumour suppressor gene to differentiate between endometriosis and ovarian cancer while monitoring the risk of malignant transformation from endometriosis to ovarian cancer." (PMID 39457531, 2024). "A growing body of evidence has illuminated that LSAMP was inactivated and loss of expression due to DNA methylation modifications and acted as a tumor suppressor gene in osteosarcoma, acute myeloid leukemia, renal carcinoma and ovarian carcinoma." (PMID 35524253, 2022). "In turn, the miR-15 and miR-16 were down-regulated in ovarian cancer tissues, whereas miR-31 was expressed at low levels in serous ovarian cancer cells and tissues, suggesting its role as a tumor suppressor gene of ovarian cancer." (PMID 31035447, 2019). "PTCH2 is a membrane receptor, member of the Hedgehog signaling pathway, and has been associated with proliferation-related disorders such as endometriosis and ovarian carcinoma, playing a role as a tumor suppressor gene." (PMID 29118976, 2017). "Taken together, our data demonstrate that KLF4 functions as a tumor suppressor gene in ovarian cancer cells by inhibiting TGFβ-induced EMT." (PMID 25137052, 2014). "In summary, we have identified a number of Notch proteins as key transcriptional targets of the breast/ovarian cancer tumour suppressor gene BRCA1." (PMID 23863842, 2013). "Our results support a role for SFRP4 as a tumor suppressor gene in ovarian cancers via inhibition of the Wnt signaling pathway." (PMID 22363760, 2012). "Dabholkar and colleagues found that the mRNA level of some DNA repair gene was significantly increased in platinum-resistant ovarian carcinoma, indicating that the level of DNA repair gene expression correlates with the response to platinum-based chemotherapy." (PMID 19563645, 2009). "RPS6KA2 was also identified as a cancer suppressor gene in epithelial ovarian cancer." (PMID 34676211, 2021). "We propose a model in which MYPT1 acts as a tumor suppressor gene in ovarian cancer." (PMID 31926547, 2020). "The results indicated that miR-30b-3p was a tumor suppressor gene for ovarian cancer." (PMID 32156314, 2020).
melanoma (20 papers, 2004 to 2025). A malignant, usually aggressive tumor composed of atypical, neoplastic melanocytes. "The 10q24.33 region containing OBFC1, a known telomere maintenance gene, has been implicated in lymphocytic leukemia, melanoma, and kidney, ovarian, and thyroid cancers." (PMID 33579919, 2021). "In combination, evidence suggests that RYBP act as tumour suppressor gene in different solid tumours but as an oncogene in lymphoma and melanoma; however, the precise underlying mechanisms of these opposing function remain to be clarified." (PMID 29383875, 2018). "In our study, we found that miR-10a-5p was obviously diminished in melanoma tissues by bioinformatics method, showing that miR-10a-5p serves as a tumor suppressor gene in melanoma." (PMID 34424910, 2021). "While TFG was supposed to be a tumor-suppressive gene in melanoma, its role in melanoma has been understudied." (PMID 33066509, 2020). "Bcl-2 is an anti-apoptotic gene and has been involved in many cancers such as melanoma, breast, lung, and liver carcinomas." (PMID 31684176, 2019). "Melanoma differentiation associated gene-7 (MDA-7), also known as interleukin (IL)-24, is a tumour suppressor gene associated with differentiation, growth and apoptosis." (PMID 20735832, 2010). "Collectively, this work discovered that UTRN could act as a tumor suppressor gene in melanoma and serve as a prognostic factor." (PMID 33632212, 2021). "miRNA-23b-3p was shown to be a tumour suppressor gene in melanoma." (PMID 32993558, 2020). "Furthermore, RYBP has also been shown to act as tumour suppressor gene in different solid tumours, but as an oncogene in lymphoma and melanoma." (PMID 29383875, 2018). "In addition, we have identified that MECOM, a novel, central epigenetic regulatory gene, and TET2/IDH1, critical regulators of DNA demethylation, are frequently mutated in patient melanoma samples." (PMID 26221190, 2015). "Kiss-1 has been identified as a putative human metastasis suppressor gene in melanomas." (PMID 25111296, 2014). "Notably, INPP4B was found to serve as a tumor suppressor gene in melanoma via regulating PI3K/Akt signaling, which impacts the proliferative, invasive, and tumorigenic capacity of melanoma cells." (PMID 38474285, 2024).
hepatocellular carcinoma (15 papers, 2005 to 2022). A malignant tumor that arises from hepatocytes. "However, DKK4 expression was shown to be associated with decrease in hepatoma cells progression induced by thyroid hormones and has been marked as tumor suppressor gene in hepatocellular carcinoma." (PMID 33346226, 2020). "Our in vitro cell experiment suggested that IDH1 may act as a tumor suppressor gene in hepatocellular carcinoma in that loss-of-function of IDH1 significantly promoted hepatoma cell growth and migration; whereas overexpression of wild-type IDH1 had opposite effects." (PMID 27469031, 2016). "A recent study demonstrated that HAMP, as a tumor suppressor gene of hepatocellular carcinoma, downregulation contributes to proliferation, aggressiveness, and metastasis of hepatocellular carcinoma via the cyclin 4-dependent kinase-1/STAT3 pathway." (PMID 36585741, 2022). "GAS8-AS1 has also been regarded as a putative tumor suppressor gene in papillary thyroid cancer and hepatocellular carcinoma." (PMID 31749921, 2019). "Functional evidence and signaling pathway studies indicate that MCC acts as a tumor suppressor gene by inhibiting the oncogenic NF-κB and β-catenin pathways in CRCs and hepatocellular carcinoma." (PMID 25200342, 2014). "MiR-101 was shown to promote apoptosis and suppress FOS oncogene expression in human hepatoma cells and to act as tumor suppressor gene in carcinogenesis of human hepatoma." (PMID 20444294, 2010). "We identified two miRNAs, 101 and 29c, were induced by TPA and down regulated in human hepatoma tissues suggest that they might play as tumor suppressor gene and in tumor formation of HCC." (PMID 20444294, 2010). "In hepatocellular carcinoma, overexpression of DDX3 was observed in hepatocellular carcinoma and DDX3 was identified as a cellular transforming gene in hepatocarcinogenesis." (PMID 26087195, 2015).
osteosarcoma (12 papers, 2012 to 2023). A usually aggressive malignant bone-forming mesenchymal neoplasm, predominantly affecting adolescents and young adults. "MiR-493 has been proved to play the role of tumor suppressor gene in osteosarcoma and inhibit the cell biological process of osteosarcoma, playing an opposite role with FAM64A." (PMID 32184824, 2020). "In summary, miR-133b expression is significantly decreased in human osteosarcoma samples and is a potential tumor suppressor gene." (PMID 24391788, 2013). "It will be interesting to verify the putative target genes and further investigate the mechanism by which miR-34a functions as a tumor suppressor gene in osteosarcoma." (PMID 22457788, 2012). "Therefore, miR-652 may act as a tumor suppressor gene in osteosarcoma and provide a new target for molecular therapy of osteosarcoma." (PMID 35111226, 2022).
colon cancer (10 papers, 2014 to 2021). "Finally, ARID1A, a chromatin remodeling gene, has also been reported to be mutated in colon cancer." (PMID 26379039, 2015). "ITIH5 is also expressed by normal skin fibroblasts but not by epidermal keratinocytes and is a novel putative tumour suppressor gene in colon cancer." (PMID 30678366, 2019). "However, some studies defined miR-211 as a tumor promoter, by inhibiting the expression of SRC kinase signaling inhibitor 1 (SRCIN1), miR-211 was proved to promote human non-small cell lung cancer, and by targeting tumor suppressive gene CHD 5, miR-211 can promote human colon cancer." (PMID 28924391, 2017). "However, in other instances, DKK1 was found to be repressed in certain colon cancers and it was suggested that DKK1 might act as a tumor suppressor gene." (PMID 26545120, 2015).
leukemia (10 papers, 2010 to 2025). A malignant (clonal) hematologic disorder, involving hematopoietic stem cells and characterized by the presence of primitive or atypical myeloid or lymphoid cells in the bone marrow and the blood. "EVI1 (Ecotropic Viral Integration site I), which was originally identified as a myeloid transforming gene by means of retroviral insertional mutagenesis in mouse leukemia, encodes a nuclear DNA binding zinc finger protein." (PMID 21980434, 2011). "The TAD structural changes involve the vascular endothelial growth factor gene VEGFA, which is a major tumor angiogenic gene that is over-expressed in leukemia (see reviews for more details), consistent with the fact that K562 cells are chronic myelogenous leukemia cells." (PMID 38218905, 2024). "In acute myeloid leukemia (AML), in particular, controversial new findings indicate that HIF-1α can act either as an oncogene or a tumor suppressor gene, and this may depend on the stage of leukemia development and/or the AML sub-type." (PMID 27447550, 2016). "These suggested that PDE4DIP might be a tumor suppressor gene in leukemia." (PMID 32638549, 2020).
acute myeloid leukemia (9 papers, 2006 to 2024). Acute myeloid leukemia (AML) is a group of neoplasms arising from precursor cells committed to the myeloid cell-line differentiation. "Sprouty-related, EVH1 domain-containing protein 1 (SPRED1) has been identified as a novel tumor suppressor gene in acute myeloid leukemia (AML)." (PMID 35359401, 2022). "Mcl-1 is an important antiapoptotic gene, promoting cell survival in various hematological malignancies, including multiple myeloma (MM), acute myeloid leukemia (AML), and NHL." (PMID 34833935, 2021).
non-small cell lung carcinoma (9 papers, 2014 to 2025). A group of at least three distinct histological types of lung cancer, including non-small cell squamous cell carcinoma, adenocarcinoma, and large cell carcinoma. "Hsa-miR-361-3p, downregulated in our study, was reported to act as a tumor suppressor gene in non-small cell lung carcinoma (NSCLC)." (PMID 38326829, 2024). "Low FOXP1 expression has been reported to be associated with poor prognosis in non-small cell lung cancer, while NFAT1 has been reported to act as a tumor suppressor gene." (PMID 26465158, 2015). "In addition TFG has been identified as a putative metastatic melanoma tumour suppressor gene and is also thought to play a role in non-small cell lung cancer, acting as a translocation partner for anaplastic lymphoma kinase (ALK)." (PMID 24999993, 2014). "Its expression has been shown to be downregulated by epigenetic modification in non-small cell lung cancer and hence, RXRG is regarded as a tumor suppressor gene." (PMID 41439026, 2025).